MTOR (mechanistic target of rapamycin kinase)
Diseases named in the same sentence as MTOR in open-access papers (continued):
Sharing a sentence is not in itself a finding about the gene and the disease.
hepatocellular carcinoma (continued). "The signal transducer and activator of transcription 3 (STAT3) regulates glucose metabolism in hepatocellular carcinoma (HCC) through the HK II mTOR-mediated pathway, contributing to the development of HCC." (PMID 38202657, 2023). "In this review, our aim is to provide an overview of the tumor-promoting effects exerted by the PI3K/AKT/mTOR signaling pathway in hepatocellular carcinoma (HCC), which is primarily triggered by the epidermal growth factor receptor (EGFR)." (PMID 37631344, 2023). "This led to an increase in PTEN levels, inhibiting the AKT/mTOR pathway, thus activating autophagy in hepatocellular carcinoma (HCC)." (PMID 36899946, 2023). "A study of hepatocellular carcinoma (HCC) cells from patients showed that siRNA-mediated knockdown of eEF1A2 expression diminished the activation of both Akt and mTOR signaling, suggesting that eEF1A2 is an upstream inducer of PI3K." (PMID 37051183, 2023). "In this study, we aim to develop and validate a radiomics model for pretreatment prediction of RPS6K expression in hepatocellular carcinoma (HCC) patients, thus helping clinical decision-making of mTOR-inhibitor (mTORi) therapy." (PMID 37482600, 2023). "The sequential treatment of phenformin and mTOR inhibitors strikingly led to a dramatic improvement in the survival of orthotopic xenograft mice of human hepatocellular carcinoma (HCC)." (PMID 38132178, 2023). "The results of KEGG indicated that the 40 differential expressed FRGs were manly enriched in the longevity regulating pathway, AMPK signaling pathway, the mTOR signaling pathway, and hepatocellular carcinoma, highlighting their roles in HCC progression." (PMID 36873737, 2023). "Meanwhile, the phosphorylation of mTOR at Ser2448 and Ser2481 markedly suppressed the survival of hepatocellular carcinoma (HCC) cells." (PMID 35186488, 2022). "Genistein could reverse drug resistance of 5-fluorouracil-resistant hepatoma cell line Bel-7402/5Fu by up-regulating the expression of Akt and mTOR in PI3K/Akt/mTOR pathway, down-regulating the expression autophagy-related genes of Beclin and LC3 to promote cell autophagy." (PMID 35646647, 2022). "In addition, we found that NAP1L5 may inhibit the progression of hepatocellular carcinoma by inhibiting the PI3K/AKT/MTOR signaling pathway." (PMID 36374212, 2022). "Hydrogen sulfide induces autophagy of hepatocellular carcinoma cells (HCC) by inhibiting the phosphatidylinositol 3-kinase (PI3K)/protein kinase B (AKT)/ mTOR (PI3K/Akt/mTOR) signaling pathway." (PMID 35204209, 2022). "Some matrine derivatives can also inhibit the proliferation of hepatocellular carcinoma (HCC) cells through the PI3K/AKT/mTOR and AKT/GSK3/β-catenin signaling pathway." (PMID 35684449, 2022). "Similarly, a previous study about hepatocellular carcinoma suggested that the activation of the AKT/mTOR pathway could elevate the expression of SREBP1-c and then reprogram hepatic lipid metabolism." (PMID 36548730, 2022). "Furthermore, a previous study about hepatocellular carcinoma suggests that activation of the Akt/mTOR pathway could elevate the expression of FAO regulator SREBP1c and then reprogram hepatic lipid metabolism." (PMID 35464439, 2022). "Therefore, SSd increases radiation-induced apoptosis of hepatoma cells, which may be related to promoting autophagy via inhibiting mTOR phosphorylation." (PMID 33628104, 2021). "The endocytosed AFP can interact with PTEN and activate the PI3K/AKT/mTOR pathway, which promotes the malignant behavior of hepatocellular carcinoma (HCC) cells by upregulating the protein expression of mTOR." (PMID 33718192, 2021). "Clinical evidence has strongly supported the negative regulatory role of CBS in proliferative diseases, which induces autophagy and apoptosis via the PI3K/Akt/mTOR pathway in hepatocellular carcinoma (HCC) cells." (PMID 33995034, 2021). "And its anticancer mechanism in hepatocellular carcinoma may be via AKT/mTOR pathway." (PMID 34527062, 2021).
hepatocellular carcinoma (continued). "mTOR inhibitors have been reported to have therapeutic effects on hepatocellular carcinoma (HCC) through multiple mechanisms, including direct antitumor effects and immune regulation." (PMID 32849546, 2020). "Previous studies have reported that the expression of Akt in PLC cells is significantly higher than that in normal liver tissues, and Chinese materia medicas could regulate the PI3K/Akt/mTOR signaling pathway to induce cell apoptosis and inhibit the growth of hepatoma cells." (PMID 32382293, 2020). "USP10 inhibits hepatocellular carcinoma (HCC) growth in vivo by inhibiting the mTOR signaling pathway." (PMID 33277473, 2020). "SAB has been found to induce apoptosis and autophagy by inhibiting AKT/PI3K mediated activation of mTOR pathway in colorectal and hepatocellular carcinoma (HCC) cells." (PMID 36046777, 2020). "Dysregulated oncomiRs are attributed to hepatocellular carcinoma (HCC) through targeting mTOR signaling pathway responsible for cell growth and proliferation." (PMID 33614488, 2020). "However, the dual effects of immunosuppressive and antitumor effects of phloretin are more suitable as immunosuppressive drugs for liver transplantation in patients with hepatocellular carcinoma or kidney transplantation in patients with renal cancer, just like rapamycin (a kind of mTOR inhibitor)." (PMID 32802861, 2020). "In hepatocellular carcinoma (HCC), the microRNA miR-26a can reduce tumor growth by suppressing the Akt/mTOR pathway through targeting ST3GAL6." (PMID 31117943, 2019). "Primary or acquired resistant mechanisms prevent the employment of individualized therapy with target drugs like the mTOR inhibitor everolimus (EVE) in hepatocellular carcinoma (HCC)." (PMID 31406139, 2019). "Other groups showed that downregulation of the AKT1/mTOR-axis using the histone deacetylase inhibitor suberoylanilide hydroxamic acid (SAHA) induced ACD in hepatocellular carcinoma (HCC) cell lines." (PMID 31671879, 2019). "This suggests that mTOR may be a potential target for the treatment of hepatocellular carcinoma." (PMID 30526568, 2018). "In addition, recent studies demonstrated an unanticipated role for p62 in activation of the mammalian target of rapamycin (mTOR) pathway; which is a central regulator of cell growth and autophagy, and is aberrantly activated in many types of cancer such as hepatocellular carcinoma." (PMID 25870850, 2015). "Moreover, induction of cell cycle arrest by miR-99a may suppress expression of insulin-like growth factor 1 receptor (IGF-1R) and mammalian target of rapamycin (mTOR) in hepatocellular carcinoma cells." (PMID 24637915, 2014). "In human hepatocellular carcinoma (HCC), de novo lipogenesis has been found to be increased and associated with the activation of AKT/mTOR signaling." (PMID 24069385, 2013). "PP2A dephosphorylates pAkt and CIP2A enhances PI3K/mTor signalling by inhibiting PP2A mediated dephosphorylation of pAKT in hepatocellular carcinomas (HCC)." (PMID 24098375, 2013). "Mammalian target of rapamycin (mTOR) and the microtubules are shown to be potential targets for treating hepatocellular carcinoma (HCC)." (PMID 23509629, 2013). "Due to the frequent dysregulation of the PI3K/AKT/mTOR signaling pathway, mTOR represents a suitable therapeutic target in hepatocellular carcinoma (HCC)." (PMID 23167739, 2012). "This study investigates the in vitro antitumor activity of C. amuricus fractionated extracts against hepatocellular carcinoma cells, coupled with molecular docking analysis targeting key components of the PI3K/AKT/mTOR signaling axis." (PMID 41511947, 2026). "In hepatocellular carcinoma cells, quercetin treatment downregulated proline 4-hydroxylase (P4HA2) and inhibited the PI3K/Akt/mTOR signaling pathway, leading to pronounced apoptosis." (PMID 40808836, 2025).
hepatocellular carcinoma (continued). "Studies have demonstrated that HDW can effectively inhibit the activation of the AKT/mTOR pathway in hepatocellular carcinoma (HCC) cells without causing significant hepatorenal toxicity or weight loss." (PMID 39806972, 2025). "Specifically, the SphK1/S1P axis promotes hepatocellular carcinoma (HCC) cell proliferation, survival, and migration through the activation of the PI3K/AKT/mTOR and MAPK/ERK signaling pathways." (PMID 41234914, 2025). "The crosstalk between mTOR and its upstream regulatory factors Notch, Hedgehog, and Hippo impacts the occurrence and development of NAFLD‐related hepatocellular carcinoma." (PMID 40433113, 2025). "This proposed combination of cisplatin and palbociclib (C + P) holds promise for treating hepatocellular carcinoma (HCC) patients with specific molecular characteristics, particularly those with cisplatin-resistant tumors, PTEN loss or PI3K/AKT/mTOR hyperactivation, and RB1-proficient tumors." (PMID 40456804, 2025). "Notable examples include circHGF, which encodes C-HGF to activate c-MET signaling and promote glioblastoma growth, and circZKSCAN1, which suppresses hepatocellular carcinoma through its interaction with FBXW7 and mTOR, thereby inhibiting the PI3K/AKT pathway." (PMID 40730815, 2025). "For example, circZKSCAN1 encodes a 206-amino-acid polypeptide through an IRES-driven open reading frame (ORF) to promote the ubiquitination of mTOR, thereby inhibiting the PI3 K/AKT/mTOR pathway in hepatocellular carcinoma." (PMID 40296024, 2025). "Baill, has been found to exert its anti-hepatocellular carcinoma effects by inducing mitochondrial dysfunction and ferroptosis through the activation of the AMPK/mTOR signaling pathway." (PMID 40386780, 2025). "The previous study showed that TA induced autophagic death of various tumor cells including hepatocellular carcinoma HepG2/2.2.15 and gastric cancer HGC-27 cells by inhibiting mTOR through PI3K/AKT signaling pathway." (PMID 41150819, 2025). "In hepatocellular carcinoma, the most common form of primary liver cancer, AKR1B1 has been shown to bind the kinase domain of AKT1, leading to activation of the AKT/mTOR pathway." (PMID 41154825, 2025). "miR-99b has also been reported to suppress M2 macrophage polarization by repressing the mTOR/IRF4 axis, leading to tumor regression characterized by increased CD8+ T-cell infiltration and reduced MDSC and Treg populations in hepatocellular carcinoma." (PMID 41550951, 2025). "For example, in fibrotic livers, the upregulation of integrin expression, upon binding with collagen, activates the PI3K/Akt/mTOR and FAK/ERK pathways, thereby promoting the invasion and growth of hepatocellular carcinoma." (PMID 40438115, 2025). "HCC data was assessed using survival analysis to measure PTEN, PI3K/AKT/mTOR pathway, β-catenin/BCL2, and β-catenin/HSP90 effect on prognosis of hepatocellular carcinoma patients using Kaplan–Meier (KM) plots." (PMID 40456804, 2025). "In hepatocellular carcinoma, activation of the AKT/mTOR signaling pathway promotes tumor cell clonability and survival potential and metabolic alterations, leading to poor prognosis." (PMID 41145484, 2025). "In hepatocellular carcinoma, AKR1B1 promotes tumorigenesis by interacting directly with key components of the AKT/mTOR signaling pathway." (PMID 41154825, 2025). "Que reduces HK2 levels in hepatocellular carcinoma (HCC), suppressing HK2-dependent glycolysis and AKT/mTOR signaling to inhibit progression." (PMID 40832602, 2025). "In hepatocellular carcinoma models, the dual PI3K/mTOR inhibitor PKI-587 and the natural compound Tenacissoside H (TEH) demonstrated radiosensitization potential." (PMID 40725100, 2025). "In hepatocellular carcinoma, oestradiol inhibits autophagy and promotes pyroptosis in HCC cells by activating the AMPK/mTOR signalling pathway." (PMID 38499622, 2024).
hepatocellular carcinoma (continued). "Piezo-CAP, a cold atmospheric plasma technology, effectively suppresses hepatocellular carcinoma by inducing apoptosis and autophagy through targeting redox balance, glycolysis, and the PI3K/AKT/mTOR/HIF-1α signaling pathways." (PMID 39315094, 2024). "In hepatocellular carcinoma, SAE1 expression is also upregulated, which promotes cancer cell proliferation, invasion, and metastasis by enhancing mTOR sumoylation." (PMID 39742381, 2024). "Ginsenoside Rk1 inhibits hepatocellular carcinoma progression by activating toxic autophagy and apoptosis via the AMPK/mTOR pathway, presenting a promising new treatment strategy for HCC." (PMID 39315094, 2024). "SPRY2 is an important molecule for signal regulation in vivo, and the deletion of SPRY2 can lead to the activation of the PI3K/Akt/mTOR and MAPK/ERK signaling pathways, promote cell proliferation and migration, and lead to the development of hepatoma in vivo." (PMID 39742261, 2024). "Its affinity towards Mac-2-binding protein (being produced by stromal cells of cirrhotic liver and correlating with hepatocellular carcinoma (HCC) via galectin-3/mTOR pathway enhancement) due to increased branching and decreased sialylation has been shown to be a promising biomarker of HCC." (PMID 39594740, 2024). "Platelets enhance hepatocellular carcinoma metastasis by promoting epithelial-mesenchymal transition and cancer cell autophagy through the TGF-β1/AMPK/mTOR pathway." (PMID 39315094, 2024). "Inhibition of the Akt/mTOR pathway by FOXK1 reduces cell viability and glycolysis in hepatocellular carcinoma cells." (PMID 39764438, 2024). "The procaine significantly reduced the invasion and migration of hepatocellular carcinoma cells and inhibited the epithelial-mesenchymal transition (EMT) process by induced c-Met and its downstream oncogenic pathways, such as PI3K/AKT/mTOR and MEK/ERK." (PMID 38482052, 2024). "The inhibition of glycolysis mediated by enhanced AMPK/mTOR signaling pathway signaling inhibits the activity of glycogen synthase kinase-3 beta (GSK-3β), which can suppress the acquisition of the malignant hepatocellular carcinoma (HCC) phenotype." (PMID 38482052, 2024). "In human hepatocellular cancer, 5-HT activates downstream signals, p70S6K and 4E-BP1, of the mammalian target of rapamycin (mTOR) in a mTOR- independent manner, and it inhibits autophagy." (PMID 39405338, 2024). "In hepatocellular carcinoma (HCC), the competitive binding of high-mobility group box 1 (HMGB1) and RICTOR in the mTOR pathway to miR-200 family members, such as miR-429, supports tumor self-renewal, tumorigenesis, and glutamine metabolism." (PMID 39724442, 2024). "Activation of the PI3K/Akt/mTOR pathway contributes to HCC progression in liver fibrosis and hepatocellular carcinoma cells." (PMID 39055491, 2024). "Nicotinamide mononucleotide (NMN) inhibits hepatocellular carcinoma progression by increasing NAD+ levels, enhancing apoptosis, autophagy, and ferroptosis, and activating the AMPK/mTOR pathway, suggesting its potential as a therapeutic agent for HCC." (PMID 39315094, 2024). "The baculovirus-mediated endostatin and angiostatin fusion protein (BDS-hEA) inhibits hepatocellular carcinoma growth and angiogenesis by inducing autophagy through the AMPK/AKT/mTOR signaling pathway, enhancing its therapeutic efficacy." (PMID 39315094, 2024). "Transcriptome analyses showed downregulation of mTORC1 signaling and cholesterol homeostasis, which was confirmed by weakened phosphorylation of mTOR and decreased activated SREBP1 in Gpr180KO mice and a human hepatoma cell line (Huh7)." (PMID 36726016, 2023). "In a hepatocellular carcinoma model, 6-shogaol induced apoptosis by inhibiting the AKT/mTOR/MRP1 pathway, thus exhibiting apoptotic phenomena such as smaller nuclei, condensation of chromatin around the nuclear membrane, and rupture of the nucleus." (PMID 37875983, 2023).
hepatocellular carcinoma (continued). "More recently, it has been documented that GSTA1-1 negatively regulates the mTOR signaling pathway and the over-expression of the isoenzyme in hepatocellular carcinoma cells showed enhanced AMPK activity and subsequent inhibition of the mTOR pathway." (PMID 37189435, 2023). "The results indicated that tight junction, mTOR, insulin, PI3k-AKT, hepatocellular carcinoma, FoxO, and apoptosis pathways (p < 0.05) were the possible druggable signaling pathways of CVM-1125." (PMID 37351538, 2023). "Tumor necrosis factor-alpha inhibits the key regulator of energy homeostasis AMP-activated protein kinase (AMPK) and its downstream pathway mTOR/SREBP1, inducing lipid accumulation in human hepatoma HepG2 cells." (PMID 36969840, 2023). "For example, TRIP13 plays an oncogenic role in glioblastoma via the FBXW7/c-MYC pathway and induces hepatocellular carcinoma (HCC) cell migration, invasion, and metastasis through AKT/mTOR signaling via and interaction with ACTN4." (PMID 38012658, 2023). "In hepatocellular carcinoma, miR-149 serves as a tumor inhibitory miRNA and inhibits tumorigenesis by regulating the AKT/mTOR cascade." (PMID 37744277, 2023). "Furthermore, modified miR-199a derived from AD-MSC exosomes can improve hepatocellular carcinoma (HCC) chemosensitivity through the mTOR signaling pathway." (PMID 36834969, 2023). "For this purpose, in this study, we tried to evaluate the antitumor effects of ALOF against DEN‐induced hepatocellular carcinoma in Wistar rats through antioxidative, anti‐inflammatory, mitochondrial apoptosis and PI3K/Akt/mTOR signaling pathways." (PMID 37576045, 2023). "We and others previously displayed the induction of both apoptosis and autophagy by juglone via the interaction with the different cellular signaling pathways such as the PI3K/AKT/mTOR in bovine oocytes and the MAPK pathway in hepatocellular carcinoma." (PMID 37174512, 2023). "Meanwhile, the JAK/STAT pathway, PI3K/Akt/mTOR pathway, Ras/Raf/MAPK pathway, and Wnt/β-catenin pathway contributed to hepatocellular carcinoma by regulating the cell growth, differentiation, apoptosis, and survival." (PMID 36765810, 2023). "In orthotopic mouse models of hepatocellular carcinoma (HCC), the IV injection of EVs-miR-199a loaded by the lentivirus transfection of adipose-tissue derived MSCs improved HCC chemosensitivity to doxorubicin via mTOR pathway targeting." (PMID 36839879, 2023). "A meta‐analysis indicated that mTOR improves recurrence‐free survival and reduces the recurrence rate compared with CNI in liver transplant patients with hepatocellular carcinoma." (PMID 37351559, 2023). "To determine the signaling pathway activated by B. coagulans MZY531 in H22 hepatocellular carcinoma cells, we detected the expression of PI3K/AKT/mTOR pathway-related proteins." (PMID 37705007, 2023). "Sinulariolide (from the soft coral Sinularia flexibilis) not only inhibited the migratory and invasion capacity (8 μg/mL, 24–48 h) of HA22T hepatocellular carcinoma cells, but additionally reduced the protein levels of p-ERK, p-JNK, p-p38, p-AKT, and p-mTOR." (PMID 38132936, 2023). "MCM7 inhibition led to a decrease in the esophagus and hepatocellular carcinomas viability, colony-forming ability, and migration capacity due to reducing phosphorylation of AKT1 and mTOR proteins with decreasing CDK1, CCNE1, and CCNE2 expression levels." (PMID 37529110, 2023). "In hepatocellular carcinoma, silibinin has been found to effectively abate hepatocarcinogenesis and hepatocellular carcinoma growth by regulating various signaling pathways including HGF/c-Met, Wnt/β-catenin and PI3K/Akt/mTOR." (PMID 37456742, 2023). "The genes in clusters 5 and 12 were enriched in functions related to the following KEGG pathways: cell cycle, NF‐κB, hepatocellular carcinoma, MAPK, pathways in cancer, VEGF, Rap1, TNF, TGF‐β, Wnt, AMPK, mTOR, PI3K‐Akt, HIF, and Hippo signaling." (PMID 37085918, 2023).